FANCG (FA complementation group G)
Description:
DNA repair protein that may operate in a postreplication repair or a cell cycle checkpoint function. May be implicated in interstrand DNA cross-link repair and in the maintenance of normal chromosome stability. Candidate tumor suppressor gene.
Synonyms: XRCC9; FAG
Tractability: PROTAC: ubiquitination databases record sites on it.
Gene: Protein-coding gene on chromosome 9 (35,073,820 to 35,082,444, reverse strand). Ensembl gene ENSG00000221829.
Subcellular location: Nucleus; Cytoplasm
Subcellular location (Human Protein Atlas): Nuclear speckles
Pathways (Reactome):
DNA Repair: Fanconi Anemia Pathway
Immune System: PKR-mediated signaling
Gene Ontology:
Molecular function: protein binding; damaged DNA binding
Biological process: mitochondrion organization; DNA damage response; DNA repair; interstrand cross-link repair
Cellular component: chromatin; Fanconi anaemia nuclear complex; mitochondrion; nuclear speck; cytosol; nucleoplasm; cytoplasm; nucleus
Genetic constraint (gnomAD): Loss-of-function variants: 69 observed, 80.26 expected, observed/expected ratio (o/e) 0.86, 90% interval 0.71 to 1.05. The upper end of that interval is the gene's LOEUF score, 1.05, which puts it in group 4 of 6, group 1 being the genes least tolerant of losing a copy. Missense variants: 627 observed, 762.13 expected, observed/expected ratio (o/e) 0.82, 90% interval 0.77 to 0.88. Synonymous variants: 287 observed, 326.71 expected, observed/expected ratio (o/e) 0.88, 90% interval 0.8 to 0.97.
Gene-disease validity (ClinGen):
ClinGen rates the evidence that FANCG causes each of these diseases.
Fanconi anemia complementation group G (autosomal recessive): Definitive. Fanconi anemia complementation group G is a protein encoded by the FANCG gene in humans.
Homologues: Orthologues: chimpanzee FANCG (99% identical), dog FANCG (81% identical), rabbit FANCG (80% identical), pig FANCG (79% identical), guinea pig FANCG (76% identical), mouse Fancg (72% identical), rat Fancg (72% identical), tropical clawed frog fancg (34% identical), zebrafish fancg (27% identical).
Diseases named in the same sentence as FANCG in open-access papers:
FANCG is named in the same sentence as 48 diseases in open-access papers, as found by Europe PMC text mining. Sharing a sentence is not in itself a finding about the gene and the disease. The quoted sentences say what the papers report.
Fanconi anemia (39 papers, 2010 to 2026). Fanconi anemia (FA) is a hereditary DNA repair disorder characterized by progressive pancytopenia with bone marrow failure, variable congenital malformations and predisposition to develop hematological or solid tumors. "FANCG, together with established breast/ovarian predisposition genes BRCA1 and BRCA2 belongs to the Fanconi anemia gene family; however, little is known about cancer predisposition in carriers of FANCG germline alterations." (PMID 39149814, 2024). "The third fetus (case 8) presented with intrauterine growth restriction, oligodactyly of the left hand and a hypoplastic ray of the right hand and was diagnosed with Fanconi anemia (FA) due to a homozygous FANCG nonsense variant (OMIM# 614082)." (PMID 36900003, 2023). "It is intriguing that Fanconi anemia patients, including those with mutations in FANCG, are associated with the development of myeloid leukemias." (PMID 36292578, 2022). "A FANCG mutation has been identified in patients with Fanconi anemia of complementation group G." (PMID 38310280, 2024). "A double heterozygous frameshift and missense pathogenic variant in DDB2 and FANCG genes, respectively were identified in a patient with endometrial cancer, which contrasts to the reported associated phenotype for these variants (Xeroderma pigmentosum and Fanconi anemia, respectively)." (PMID 36428697, 2022). "In this study, Fanconi anemia was genetically confirmed in 19 individuals, with the majority of pathogenic or likely pathogenic variants identified in the FANCA, FANCG, and FANCC genes." (PMID 41520327, 2026). "Of the 19 patients diagnosed with Fanconi anemia, the majority of mutations were found in the FANCA gene (n = 12), followed by FANCG (n = 4) and FANCC (n = 3)." (PMID 41520327, 2026). "While Fanconi Anemia-associated genes BRCA2, FANCA and PALB2 are known PCa GT candidates, FANCD2 outranked FANCA, with FANCG, ECCR4, FANCE and FANCI (in order of ranking) potential candidates." (PMID 41038821, 2025). "Mutations in the Fanconi anemia (FA) pathway were present in 33.3% of patients, predominantly involving FANCA, FANCI, and FANCG." (PMID 40805139, 2025). "FANCG was shown to play an important role in the activation of the Fanconi anemia (FA) pathway with the localization of the nuclear FA complex (including FANCG), and it can also interact with FANCD1 (BRCA2)." (PMID 35488336, 2022). "Another interesting finding in our cohort is the high incidence of monoallelic variants in other Fanconi anemia (FA) genes: FANCA, FANCC, FANCD2, RAD51C, FANCG and FANCI." (PMID 36290365, 2022). "Complementation studies showed that the FANCG gene from the Fanconi Anaemia/BRCA (FA/BRCA) DNA repair pathway was impaired, indicating that the variant in FANCG contributes to the cellular phenotype." (PMID 35052418, 2021). "FANCA and FANCG (XRCC9) interact with each other and participate in the repair of interstrand crosslinks and DSBs via the Fanconi anemia pathway." (PMID 34573315, 2021). "Most fanconi anemia patients harbour homozygous or double heterozygous mutations in the FANCA (60-65%), FANCC (10-15%), FANCG (~10%) or FANCD2 (3-6%) genes." (PMID 29400309, 2018). "NHEJ mutants were the most radiation sensitive cells, followed by HR mutants, PARP, and FANCG (Fanconi Anemia complementation group G) mutants, with the CHO of wild type being the most radioresistant." (PMID 30061540, 2018). "PBX3 has been reported to be over-expressed in prostate cancer, whilst FANCG belongs to a group of proteins known as the Fanconi anemia complementation family and has been reported to be important in DNA damage repair pathways." (PMID 23737949, 2013). "Moreover, 14% of the patients included in this study harbored deleterious mutations in Fanconi anemia genes (FANCA, FANCD2, FANCF, FANCG FANCI and FANCL) and in WRN, which have been reported to interact with BRCA1." (PMID 38184614, 2024).
Fanconi anemia (continued). "Notably, we detected germline pathogenic variant in Fanconi anemia (FA) complementation group I (FANCI) and group G (FANCG), which are involved in repairing DNA double-strand breaks by homologous recombination, for the first time, in ECS blood samples." (PMID 39158654, 2024). "Since the generation of HAP1 FANCG and FANCM knockout cell lines has also been reported recently, loss of expression of Fanconi anemia-associated genes might rather slow down cellular proliferation than directly inducing cell death." (PMID 33228647, 2020). "In CRC, significant associations of HR (BRCA1, BRCA2, BARD1, PALB2 and BRIP1) and Fanconi anaemia (FANCA, FANCC and FANCG) genes with TMB were identified." (PMID 37821580, 2023). "Furthermore, radiobiologic studies in tumors bearing Fancd2−/− and FancG−/− mice may lead to the clinical translation of JP4-039/F15 as a potential radioprotectant during radiotherapy of Fanconi anemia patients, or other patients with genetic defects in DNA repair." (PMID 24596683, 2014). "Other common genetic etiologies associated with EA/TEF include chromosomal disorders (trisomy 21, trisomy 18, trisomy 13), Feingold syndrome (MYCN), Fanconi anemia (multiple genes including FANCB, FANCC, FANCG, BRIP1) and other recurrent deletion and duplication syndromes." (PMID 36909054, 2023). "Relevant to the adaptation of TRD to arid conditions, ten selected genes (including SLX4, FANCF, FANCG, FANCI, ATR, and POLH) were related to the fanconi anemia pathway (bta03460, p < 0.01) involved in DNA repair, DNA replication fork stability, and other cellular processes." (PMID 33072165, 2020). "Among DNA repair genes, we detected a high presence of members of the Fanconi Anemia Complementation Group (FANCC, FANCD2, FANCG, FANCA, and FANCE), which participate in homologous recombination DNA repair, and genes involved in double-strand break repair (BRCA2, BRIP1, BARD, BLM, CHEK2, and PALB2)." (PMID 30487452, 2018).
anemia (10 papers, 2015 to 2025). A reduction in the number of red blood cells, the amount of hemoglobin, and/or the volume of packed red blood cells. "FANCG is a gene encoding Fanconi anemia (FA) group G protein, and part of the FA DNA damage repair pathway and in which germline pathogenic variants often predispose to cancers." (PMID 34285288, 2021). "BRCA2, Fanconi anemia complementation group protein C (FANCC) and a combination of FANCC and Fanconi anemia complementation group protein G (FANCG) mutations have been found in pancreatic cancer patients." (PMID 28471392, 2017). "Interestingly, we found that 10 of 11 patients with lymphoma and another solid tumor harbored germline mutations in Fanconi anemia complementation group (FANC) genes, including FANCI, FANCA, FANCG, FANCL, FANCD1, FANCF, FANCJ, and FANCS." (PMID 37546421, 2023). "This mutation lies in the binding domain of the Fanconi anemia complementation group D2 (FANCD2) and CG (FANCG) proteins; thus interactions with these proteins may be impaired." (PMID 30040829, 2018). "FANCM is the most highly conserved member of the Fanconi Anemia complementation group (FANCG)." (PMID 28591191, 2017). "Additionally, we found a clique that consists of Fanconi anemia (FA) proteins (FANCF, FANCM, FANCG and FANCD2) and a third clique with two FA proteins together with BLM and RMI2." (PMID 38909016, 2024).
breast carcinoma (7 papers, 2012 to 2025). "Regarding FANCG gene, although it is usually included in the genetic diagnostic panels for hereditary breast cancer, its contribution to the genetic susceptibility of the disease is not well defined." (PMID 38313678, 2024). "The FANCG frameshift variant, c.637_643del p.(Tyr213LysfsTer6), detected in two breast cancer patients (BRB98 & BRB225), is a founder variant that is present in 82% of Fanconi anaemia subtype G patients from sub-Saharan African populations." (PMID 35039564, 2022). "Two missense variations in FANCC and FANCG genes, predicted to be deleterious, were further identified in breast cancer cases with family history of different tumors including leukemia, breast, prostate, and colon cancers." (PMID 38313678, 2024). "We extracted seven genes, XRCC3, XRCC2, RAD51C, RAD51L1, RAD51L3, FANCG, BRCA2, that formed a connected PPI network with eight interactions, and had been associated with breast cancer as well as other types." (PMID 24784581, 2014).
ovarian carcinoma (7 papers, 2008 to 2024). A malignant neoplasm originating from the surface ovarian epithelium. "A study in ovarian cancer has identified increases in FANCG mRNA expression associated with the acquisition of a chemoresistant phenotype in ovarian cancer cells." (PMID 36046263, 2020). "Other members of the FANCG complementation group include breast and ovarian cancer associated genes; FANCO (RAD51C), FANCS (BRCA1), BRCA2 (FANCD1), BRIP1 (FANCJ) and PALB2 (FANCN)." (PMID 28591191, 2017).
pancreatic cancer (6 papers, 2010 to 2024). "The report pointed out that FANCG and FANCA heterozygous mutations were susceptible to haematological malignancies and pancreatic cancer." (PMID 32762026, 2020). "In comparison, genetic inactivation of the proximal FA pathway appears to occur infrequently in tumors among the general population and has, in terms of GI cancers, yet only been reported in pancreatic cancer, where it was associated with rare mutations in FANCC or FANCG." (PMID 20509860, 2010). "Additionally, we included FANCG and FANCF in these analyses, as FANCG represents another proximal FA gene that has been described to be mutated in GI cancer, specifically in pancreatic cancer, while FANCF has been reported to be epigenetically inactivated in various tumor types." (PMID 20509860, 2010). "However, germline and somatic changes in FANCC and FANCG may have comparatively low penetrance for pancreatic cancer, which is supported by studies investigating germline mutations of upstream FA pathway genes in sporadic, yet FA-typical tumors among the general population." (PMID 20509860, 2010).
prostate carcinoma (3 papers, 2013 to 2021). A carcinoma that arises from epithelial cells of the prostate gland. "FANCG has been identified as being significantly differentially regulated post irradiation in prostate cancer cells." (PMID 34830778, 2021). "While BRCA1, FANCG and RAD51 have previously been linked to various treatment responses in a number of cancers limited research exists investigating the association between RT-induced regulation of these genes in radiation resistant prostate cancer." (PMID 25369795, 2014).
colon cancer (2 papers, 2022 to 2024). "More specifically, the APEX1 signaling pathway plays a crucial role in regulating colon CSC growth, whereas FEN1, FANCG and RAD23B were up-regulated in chemo-resistant human colon cancer cell lines." (PMID 35805102, 2022).
melanoma (2 papers, 2007 to 2016). A malignant, usually aggressive tumor composed of atypical, neoplastic melanocytes. "In line with a crosstalk between MiTF and the FANC pathway, MiTF silencing in melanoma cells triggered a strong reduction in the mRNA level of 4 analysed FANC genes: FANCA, FANCD2, FANCC and FANCG." (PMID 27827420, 2016). "FANCA and FANCL mRNAs were clearly upregulated in E2F1 overexpressed SKMEL-2 melanoma cells, whereas FANCD1 and FANCG mRNAs were unchanged after E2F1 overexpression." (PMID 19936073, 2007).
acute myeloid leukemia (1 paper, 2022). Acute myeloid leukemia (AML) is a group of neoplasms arising from precursor cells committed to the myeloid cell-line differentiation. "Concerning the hematologic phenotype, patients with FANCG PV have been found to have more severe cytopenia as well as a higher frequency and an earlier diagnosis of acute myeloid leukemia or myelodysplastic syndrome than patients with FANCA or FANCC genotypes." (PMID 35216452, 2022).
colorectal tumor (1 paper, 2021). "Among these, 2 genes were affected by high-confidence LoF germline variants: FANCG (germline splice site variant, c.307 + 1G > C) in gastric tumor of dou_004 and CASP8 (germline deletion variant, c.658_659del) in colorectal tumor of dou_010." (PMID 34285288, 2021).
esophageal squamous cell carcinoma (1 paper, 2022). Esophageal squamous cell carcinoma (ESCC) is a type of esophageal carcinoma (EC) that can affect any part of the esophagus, but is usually located in the upper or middle third. "Through further study of the mechanism, we found that niraparib tosylate has a radiosensitization effect on esophageal squamous cell carcinoma cells by down-regulating FANCG expression in FA-BRCA pathway." (PMID 35364771, 2022).
hereditary cancer (1 paper, 2020). Malignant neoplasms occurring in families at a rate greater than that expected by chance and caused by germline mutations in a specific gene. "A prospective cohort of 1021 unrelated cancer cases with clinical suspicion of hereditary cancer was screened for mutations in the following 14 FA genes: FANCA, FANCB, FANCC, FANCD2, FANCE, FANCF, FANCG/XRCC9, FANCI, FANCL/PHF9, FANCM, FANCP/SLX4, FANCQ/ERCC4, FANCR/RAD51 and FANCU/XRCC2." (PMID 32235514, 2020).
intrauterine growth restriction (1 paper, 2023). "The fetus with the FANCG variant came to attention through intrauterine growth restriction (IUGR), thumb hypoplasia on the left hand and absent thumb on the right hand." (PMID 36900003, 2023).
microcephaly (1 paper, 2024). A congenital or acquired developmental disorder in which the circumference of the head is smaller than normal for the person's age and sex. "They showed that FANCA- and FANCG- deficient embryos developed microcephaly due to apoptosis of proliferating neural stem and progenitor cells and the resulting decline in neuron production." (PMID 39224124, 2024).
subependymal giant cell astrocytoma (1 paper, 2021). A benign, slowly growing tumor (WHO grade I) typically arising in the wall of the lateral ventricles and composed of large ganglioid astrocytes. "Furthermore, sequencing of three subependymal giant cell astrocytoma (SEGA)-like astrocytomas in NF1 mutant patients with ALT and intact ATRX have revealed genetic alterations in RECQL4, Fanconi anemia complementation group genes (FANCD2, FANCF, and FANCG), and SMARCAL1." (PMID 34069193, 2021).
testicular germ cell tumor (1 paper, 2022). A germ cell tumor arising from the testis. "We identified the c.1182_1192delTGAGGTGTTTTinsC (p.Glu395TrpfsTer5) variant in the FANCG gene in a 35-year-old male patient with a metachronous testicular germ cell tumor and squamous cell tongue cancer." (PMID 36290365, 2022).
cancer (17 papers, 2013 to 2025). A tumor composed of atypical neoplastic, often pleomorphic cells that invade other tissues. "Heterozygous FANCG GPVs have been identified episodically in cancer patients and their association with cancer risk remains uncertain." (PMID 39149814, 2024). "Interestingly, preliminary data on isogenic RKO cancer cells harbouring defects in the proximal FA pathway revealed increased TRAIL-sensitivity only upon FANCG inactivation, while FANCC deficient cells remained unaffected (our own unpublished results)." (PMID 26843614, 2016). "Pathogenic variants in five “other” cancer predisposition genes (ALK, BUB1B, FANCG, RB1 and XPC) exclusively investigated for truncating variants, were identified in seven patients." (PMID 35039564, 2022). "There is a need to further understand the involvement of DDB2, FANCG and FANCD2 with respect to cancer risk, in order to facilitate personalized medicine for the carriers." (PMID 36428697, 2022). "To explore the significance of this interface in FA and cancer, we mutated five residues of FANCA observed in FA-patients or cancer cells, and examined binding between FANCA CTD and FANCG using yeast two-hybrid analyses." (PMID 32002546, 2020). "Amplifications of 8 FA genes are identified across 22 carcinomas; 2 of the carcinomas contain amplification in two FA genes (FANCG with FANCI and BRIP1 with RAD51C)." (PMID 26438152, 2015). "Notably, 74 of these genes overlapped with well-known cancer-associated genes (CAGs), such as CCR4, KLF4, FANCG, and NAB2." (PMID 39267784, 2024). "Our studies have identified a unique FANCG variant in BMDs that results in a cellular phenotype of defective DNA repair, but is not sufficient or necessary for development of cancer in BMDs." (PMID 36292578, 2022). "The FANCG variant allele frequency is slightly higher in dogs with HS (41%) vs. dogs free of cancer at 9 years or above (36%), or dogs with other cancer (32%), but the differences are not statistically significant." (PMID 36292578, 2022). "And the lack of FANCA and FANCG expression was also associated with these two sporadic cancers." (PMID 32762026, 2020). "FANCG, PALB2 and SLX4 homozygous deletions are identified in single carcinomas while FANCM homozygous deletions are identified in 2 carcinomas." (PMID 26438152, 2015). "Of these, seven genes (BRIP1, ERCC4, FANCD2, FANCG, FANCI, MAD2L2, PPP2R2A) were previously related to the platinum sensitivity/resistance of different types of cancer cells, with NPEPPS being reported for the first time as a platinum drug sensitivity regulator." (PMID 35209078, 2022).